TNF (tumor necrosis factor)
Diseases named in the same sentence as TNF in open-access papers (continued):
Sharing a sentence is not in itself a finding about the gene and the disease.
Insulin resistance (continued). "Sustained production of TNF-α, a potent cytokine, can induce insulin resistance and impair metabolic regulation by several mechanisms." (PMID 39998445, 2025). "Dysfunctional adipocytes and M1 macrophages infiltrated into PVAT release TNF-α, which exerts atherogenic effects and promotes vascular dysfunction, insulin resistance, and dyslipidemia." (PMID 40647187, 2025). "PTX, a PDE inhibitor, reduces hepatic fat accumulation, improves lipid profiles, and ameliorates insulin resistance by inhibiting TNF-α synthesis." (PMID 39858534, 2025). "These pro-inflammatory cytokines, particularly TNF-α and IL-6, can lead to insulin resistance in adipose tissue, skeletal muscle, and the liver by disrupting insulin signaling." (PMID 40689212, 2025). "For instance, insulin receptor substrate (IRS) proteins are serine phosphorylated by TNF-α, which starts the disintegration of the insulin signaling pathway and the emergence of insulin resistance." (PMID 40013194, 2025). "This stimulates endothelial cells and immune components, triggering systemic cytokine rises (TNF-α, IL-1β, and IL-6), thereby contributing to atherosclerosis, insulin resistance, hypertension, and dyslipidemia." (PMID 41228440, 2025). "TNF-induced NF-κB activation and oxidative stress exacerbate inflammation, worsening insulin resistance." (PMID 40547917, 2025). "Among the interesting cytokines and chemokines that decreased substantially, we found the well-known and highly pro-inflammatory cytokines IL-6, TNF, and IL-18 whose roles in adipose tissue-driven inflammation and insulin resistance are well-established." (PMID 40423925, 2025). "CRP, an acute-phase protein produced by the liver, promotes the inflammatory response by increasing the synthesis of TNF-α and IL-6, which in turn contributes to insulin resistance." (PMID 40842498, 2025). "Given the known inhibitory effects of inflammatory cytokines such as IL-6 and TNFα on insulin signaling, these findings suggest that SerpinA3k expression contributes to insulin resistance through proinflammatory mechanisms." (PMID 41329353, 2025). "The production of inflammatory cytokines (such as TNF-α and IL-6) can induce insulin resistance and worsen the condition of diabetic patients." (PMID 41561166, 2025). "When adipose tissue recruits macrophages due to the overexpression of MCP1, which is a chemokine ligand known as CCL2, liver insulin resistance is observed with increased TNF-α expression in adipose tissue." (PMID 40362446, 2025). "Persistent exposure to cortisol and pro-inflammatory cytokines such as IL-6 and TNF-α enhances adipocyte differentiation and hepatic lipid accumulation, amplifying insulin resistance and dyslipidemia." (PMID 41464283, 2025). "In diabetes, adipose tissue inflammation and high serum IL-6/TNF levels are well-documented, contributing to insulin resistance and also potentially affecting the brain and behaviour." (PMID 41149069, 2025). "TNF, a potent inflammatory mediator, contributes to insulin resistance and β-cell dysfunction, and the suppression of TNF by B. heterostemon offers a promising strategy to combat the inflammatory component of T2DM." (PMID 41155161, 2025). "The overexpression of inflammatory cytokines such as TNF-α can trigger a systemic inflammatory response, further exacerbating insulin resistance and metabolic disorders." (PMID 41244040, 2025). "An elevated level of TNFα was reported in adipose tissue and systemic circulation in obesity and diabetes, contributing to the development of insulin resistance." (PMID 40868889, 2025). "With regard to metabolic syndrome, elevated IL-18 levels can contribute to insulin resistance by increasing the production of other inflammatory cytokines like TNF-α and IL-6, which interfere with insulin signaling pathways." (PMID 40277935, 2025).
Insulin resistance (continued). "In adipocytes, MIF-driven TNF-α secretion contributes to insulin resistance, while in endothelial cells, MIF disrupts insulin-mediated nitric oxide release, fostering endothelial insulin resistance." (PMID 41036138, 2025). "For instance, TNF-α manifests its effects by increasing insulin resistance through the stimulation of fatty acid release from adipose tissue into the bloodstream, directly affecting tissues such as muscle and liver." (PMID 40283443, 2025). "In the case of insulin resistance, lipolysis occurs with the release of fatty acids that activate NFκB; therefore, TNF‐α and IL‐6 are expressed." (PMID 41387361, 2025). "The IKK/NF-κB signaling pathway can be activated to increase the production of cytokines (e.g., TNF-α, IL-6, and IL-1β) to promote inflammation and insulin resistance." (PMID 40863244, 2025). "Clinically, obese patients with T2DM exhibit elevated IL-6 and TNF-α, which correlates with the severity of insulin resistance." (PMID 41226411, 2025). "This process reduces activation of TLR4, leading to lower secretion of pro-inflammatory cytokines such as TNF-α and IL-6, which are involved in insulin resistance." (PMID 40559421, 2025). "Chronic TNF-α exposure also promotes lipolysis and increases circulating saturated free fatty acids, further aggravating systemic inflammation and insulin resistance." (PMID 41463063, 2025). "In diabetes, TNF-α interferes with insulin signaling pathways, leading to insulin resistance and elevated blood glucose levels." (PMID 40283848, 2025). "This imbalance in T-helper cell subsets likely contributes to the low-grade systemic inflammation characteristic of T2DM, where elevated TNF-α levels correlate with insulin resistance and metabolic dysfunction." (PMID 41030441, 2025). "Our finding that TNF-α declined with T2D progression is unexpected, as this cytokine is typically considered a central driver of insulin resistance and metabolic inflammation." (PMID 41150807, 2025). "This cytokine, secreted by regulatory T lymphocytes, has anti-inflammatory effects, increasing insulin sensitivity and opposing the role of tumor necrosis factor (TNF)-α in inducing insulin resistance in 3T3L adipocytes." (PMID 41259454, 2025). "Inflammatory mediators such as IL-6 and TNF-α contribute to skeletal muscle protein degradation, impair anabolic signaling, and exacerbate insulin resistance." (PMID 40708651, 2025). "The pro-inflammatory cascade results in the upregulation of cytokines, such as tumor necrosis factor a (TNF-a), which are known to promote insulin resistance and pancreatic cell death." (PMID 40278304, 2025). "Chronic hyperglycemia, insulin resistance, and lipid abnormalities can also induce a persistent inflammatory state, triggering excessive release of pro-inflammatory cytokines such as TNF-α and IL-6." (PMID 40260393, 2025). "As a proinflammatory cytokine with multiple functions, TNF-α is involved in inflammatory activity and DKD-associated insulin resistance, whereas IL-6 and leptin can directly affect renal and endothelial function." (PMID 40936744, 2025). "TNF-α is a pro-inflammatory cytokine closely linked to the PCOS pathology due to its role in promoting inflammation, insulin resistance, and ovarian dysfunction." (PMID 40778261, 2025). "MMP-3 also plays an important role in free fatty acid-induced insulin resistance and angiogenesis by regulating the secretion of TNFα and VEGF." (PMID 41154592, 2025). "The effect of TSFE on inflammation-induced insulin resistance was determined by measuring glucose uptake in TNF-α-treated mature 3T3-L1 adipocytes." (PMID 40807540, 2025). "The proinflammatory cytokine TNF-α, a mediator of insulin resistance, regulates insulin resistance in T2DM and other metabolic diseases." (PMID 40864768, 2025). "TNF-α activates the adipocyte signaling pathway, which is essential for inflammation and insulin resistance." (PMID 40362446, 2025).
Insulin resistance (continued). "Excess visceral adipose tissue aggravates this situation by releasing adipokines (e.g., TNF-α, IL-6) that worsen insulin resistance and foster vascular damage." (PMID 40149704, 2025). "These cytokines, including TNF-α, IL-1β, and IL-6, not only exacerbate periodontal tissue destruction but also promote insulin resistance." (PMID 41019448, 2025). "Butyrate reduces inflammatory factors (such as TNF-α and IL-6) in adipose tissue and improves insulin resistance by inhibiting the NF-kB pathway." (PMID 40950607, 2025). "Enrichment analysis revealed involvement in TNF signaling, insulin resistance, and growth hormone pathways." (PMID 41318413, 2025). "The elevated NEFA release observed in coculture likely reflects enhanced lipolysis driven by macrophage-derived TNF-α, which contributes to insulin resistance by promoting hepatic glucose production and impairing glucose uptake in skeletal muscle." (PMID 41157128, 2025). "While theories vary, periodontal disease is thought to influence increased insulin resistance and the progression of atherosclerosis via elevated tumor necrosis factor-alpha (TNF-α) production." (PMID 41357010, 2025). "These assessments were conducted under basal conditions and following treatment with either tumor necrosis factor alpha (TNF-α) to induce insulin resistance or metformin to promote insulin sensitivity." (PMID 41574186, 2025). "In states of overproduction, TNF-α can induce insulin resistance and amplify lipolysis, contributing to NEB." (PMID 40869340, 2025). "Elevated levels of chronic inflammatory markers, such as serum interleukin (IL)-6, C-reactive protein (CRP), and tumor necrosis factor-alpha (TNF-α), are associated with lower HGS and physical function and with the development of DM and insulin resistance." (PMID 40283630, 2025). "Insulin resistance is often accompanied by the release of more pro-inflammatory cytokines from adipocytes, such as tumor necrosis factor-α, C-reactive protein, and interleukin-6, which are commonly found in EMS patients." (PMID 40004998, 2025). "These beneficial effects were accompanied by improvements in insulin resistance and a reduction in plasma leptin and TNF-α concentrations, suggesting that these biomarkers play a relevant role in hepatic fat accumulation." (PMID 40862455, 2025). "We observed a strong inverse correlation between IGF-1 and TNF-α, a key pro-inflammatory cytokine known to drive insulin resistance." (PMID 41393761, 2025). "Their results and ours indicate a role for TNF-α in insulin resistance and MetS accompanying obesity." (PMID 39837875, 2025). "Systemic inflammation in COPD contributes to insulin resistance by increasing pro-inflammatory cytokines (TNF-α, IL-6, and CRP), which impair glucose metabolism and beta-cell function." (PMID 40142617, 2025). "This activation leads to the secretion of pro-inflammatory cytokines, such as TNF-α and IL-6, which increase insulin resistance in GDM." (PMID 40724491, 2025). "Simultaneously, the pro-inflammatory milieu of MASLD, characterized by elevated cytokines like IL-6 and TNF-α, further aggravates peripheral insulin resistance and pancreatic beta-cell dysfunction, directly fueling the progression of T2DM." (PMID 41441018, 2025). "At the cellular level, elevation of TNF-α levels produced by adipocytes and/or peripheral tissues induces insulin resistance by impairing the insulin signaling pathway through serine phosphorylation." (PMID 40048497, 2025). "Overexpression of the anti-inflammatory cytokine IL-10 can protect adipocytes in insulin-sensitive tissues from TNF-α–induced insulin resistance, thereby controlling diabetes progression." (PMID 41357227, 2025). "Visceral adipose tissue promotes systemic inflammation through the secretion of tumor necrosis factor-α, interleukin-6, and other proinflammatory cytokines, which subsequently lead to insulin resistance and altered hepatic lipid metabolism." (PMID 41438141, 2025).
Insulin resistance (continued). "Systemic release of proinflammatory cytokines, particularly TNF-α and IL-6, induces insulin resistance, impairing glucose uptake by peripheral tissues and enhancing hepatic gluconeogenesis." (PMID 40615660, 2025). "Chronic systemic inflammation, mediated by cytokines, such as TNF-α, IL-6, and IL-17, plays a pivotal role in metabolic dysregulation, exacerbating insulin resistance, adipokine imbalance, and lipid dysfunction." (PMID 40137170, 2025). "TNF-induced insulin resistance in hepatocytes was mitigated by CXCR1/2 blockade through the inhibition of intracellular inflammatory pathways such as JNK and NF-κB and positive modulation of the metabolic profile of the cells." (PMID 40718478, 2025). "Studies have shown that TNF-α can activate pathways (like sphingolipid and NF-κB signaling) that impair insulin receptor autophosphorylation and promote insulin resistance in both adipocytes and skeletal muscle." (PMID 40722699, 2025). "ABE has been shown to attenuate insulin resistance, an age-related disorder, by inhibiting the pro-inflammatory cytokine TNF-α, which in turn increased insulin-stimulated glucose uptake in adipocytes." (PMID 40565158, 2025). "Our data aligns with previous research, supporting the notion that TNFα induces insulin resistance by impairing insulin signaling and reducing glucose uptake in adipocytes." (PMID 39269560, 2025). "Understanding the roles of IL-1β, TNF-α, and hyperglycemia in the interplay between inflammation and insulin resistance opens new therapeutic avenues." (PMID 40218134, 2025). "First, VAT is highly proinflammatory, producing adipokines such as leptin, TNF-α, and IL-6, which promote endothelial dysfunction, inflammation, and insulin resistance." (PMID 41141356, 2025). "As adipose tissue accumulates, an increase in cytokines such as tumor necrosis factor-α (TNF-α) and interleukin (IL)-6, as well as leptin, resistin, and lipocalin 2, has been shown to play an important role in insulin resistance and inflammation." (PMID 40422865, 2025). "Tumor necrosis factor-α and its genetic variants are implicated in the development of T2DM due to systemic inflammation, dyslipidemia, and insulin resistance." (PMID 41155523, 2025). "Studies show that overexpression of TNF-α induces insulin resistance and improves when it is neutralized." (PMID 40076851, 2025). "Adipose tissue, particularly around visceral organs, and its immune cells release pro-inflammatory cytokines such as interleukins and TNF-α, contributing to insulin resistance and tumor growth." (PMID 40756563, 2025). "Conversely, oxidative stress can damage adipose tissue, prompting the release of adipocytokines, such as TNF-α and IL-6, which induce inflammation and exacerbate insulin resistance." (PMID 40842498, 2025). "The imbalance in immune cells contributes to the persistent secretion of pro‐inflammatory cytokines, such as MCP‐1, IL‐6, and TNF‐α, which induces insulin resistance and dyslipidemia." (PMID 41479855, 2025). "CRP, produced in response to cytokines such as interleukin-6 and tumor necrosis factor-α, reflects chronic low-grade inflammation that promotes insulin resistance, endothelial dysfunction, and dyslipidemia." (PMID 41301855, 2025). "Specifically, TNF-α exacerbates insulin resistance by activating the NF-κB signaling pathway and inhibiting the action of insulin." (PMID 40351422, 2025). "Chronic hyperglycemia and insulin resistance can amplify oxidative stress and promote the release of pro-inflammatory cytokines such as IL-6 and TNF-α, leading to sustained immune activation." (PMID 41476915, 2025). "Tumor necrosis factor (TNF) is often secreted by macrophages and promotes insulin resistance and reduces insulin sensitivity by interfering with the insulin signaling pathway." (PMID 39950110, 2025). "These MΦs secrete pro-inflammatory cytokines such as TNF-α, IL-6, and IL-1β, which inhibit insulin signaling in adipocytes and promote insulin resistance." (PMID 41602577, 2025).
Insulin resistance (continued). "M1 macrophages secrete pro-inflammatory cytokines (e.g., interleukins (IL-1β and IL-6), monocyte chemoattractant protein-1 (MCP-1), and tumor necrosis factor α (TNF-α)), contributing to local and systemic inflammation and insulin resistance." (PMID 41149623, 2025). "Overall, TNF-α (a pro-inflammatory cytokine) is a key player in the inflammatory pathways that drive insulin resistance, adipose tissue dysfunction, endothelial damage, and lipid dysregulation, all of which are central to the development of metabolic syndrome." (PMID 39817379, 2025). "Among different cytokines, we selected TNF-α to confirm the effect of the proinflammatory cytokines on the differentiation of preadipocytes derived from individuals with insulin sensitivity and insulin resistance." (PMID 41574186, 2025). "TNF-α promotes hepatocyte insulin resistance via JNK-1–mediated phosphorylation of IRS-1, which disrupts downstream PI3K/AKT signaling and impairs glycogen synthesis." (PMID 40988029, 2025). "IL‐6's role in insulin resistance is exacerbated by its interaction with other cytokines like TNF‐alpha and IL‐8, which are elevated in adipocytes of insulin‐resistant individuals." (PMID 40551726, 2025). "KEGG pathway analysis revealed significant upregulation of pathways associated with protein processing in the endoplasmic reticulum (ER), TNF signaling, and insulin resistance." (PMID 40433797, 2025). "This imbalance is associated with systemic inflammation and insulin resistance, evidenced by elevated levels of C-reactive protein (CRP), interleukin-6 (IL-6), tumor necrosis factor-alpha (TNF-α), and lipopolysaccharide-binding protein (LBP)." (PMID 40308637, 2025). "It is clear from these experiments that TNF is a critical factor in steatohepatitis, and it is also suggestive that TNF is a contributor to peripheral insulin resistance." (PMID 40766326, 2025). "The inflammatory cascade is significantly represented by Tumor necrosis factor-alpha (TNF) and Interleukin-1 beta (IL1B), which drive insulin resistance and β-cell dysfunction, and are functionally linked to the AGE-RAGE signaling axis." (PMID 41361572, 2025). "Excessive expression of TNF-α has been shown to contribute to the development of insulin resistance." (PMID 40895542, 2025). "Among the different proinflammatory cytokines, TNF-α is one of the most significant mediators involved in insulin resistance development and the pathogenesis of T2DM." (PMID 40362446, 2025). "TNF-α and IL-6 are key pro-inflammatory cytokines that are consistently elevated in insulin resistance and GDM." (PMID 40722699, 2025). "In UC, the Th2/Th17 immune response extends beyond the gut, with cytokines like IL-6, TNF-α, and IL-17 playing a role in the development of adiposity and insulin resistance." (PMID 41007787, 2025). "Key pro-inflammatory mediators such as interleukin (IL)-1, IL-6, and IL-8, monocyte chemotactic protein (MCP)-1, and tumor necrosis factor (TNF)-α can induce insulin resistance." (PMID 40137141, 2025). "Adipose tissue, particularly when in excess, secretes pro-inflammatory adipokines (e.g., TNF-α, IL-6) and reduces adiponectin levels, contributing to systemic insulin resistance and hepatic steatosis." (PMID 41476919, 2025). "The chronic inflammation in adipose tissue triggered by TNF-α leads to an increase in free fatty acids, further exacerbating insulin resistance and lipid dysregulation." (PMID 39817379, 2025). "Chronic periodontitis-mediated insulin resistance and worsening of glycemic control are due to systemic inflammation and the release of pro-inflammatory cytokines such as TNF-α and IL-6 and other mediators by impairing insulin signaling pathways." (PMID 40136728, 2025). "Although leptin and adiponectin help regulate energy and metabolism, other variables such as TNF-α, IL-6, and resistin can worsen insulin resistance." (PMID 40002424, 2025).